CIRBP (cold inducible RNA binding protein)
Diseases named in the same sentence as CIRBP in open-access papers (continued):
Sharing a sentence is not in itself a finding about the gene and the disease.
pancreatic cancer (continued). "Seven genes were identified in mass spectrometry and bioinformatic analysis, all significantly downregulated in pancreatic cancer (GEO data, GSE32676), including TSPYL2, TSR1, METAP2, CYR61, EBF2, CIRBP, and TGFBR3." (PMID 38015024, 2024). "Although the expression level of CIRBP in the nucleus of cancer tissues was not significantly different from that of adjacent tissues, survival curve analysis found that pancreatic cancer patients with high nuclear CIRBP expression had longer overall survival." (PMID 36061308, 2022). "Furthermore, we found that increased or decreased CIRBP expression alone did not alter the apoptosis rates of pancreatic cancer cells not treated with gemcitabine." (PMID 34490236, 2021).
Shock (5 papers, 2017 to 2025). The state in which profound and widespread reduction of effective tissue perfusion leads first to reversible, and then if prolonged, to irreversible cellular injury. "So far, CIRBP has been detected in peripheral blood of patients suffering from septic and hemorrhagic shock with high CIRBP concentrations correlating with a poor survival rate." (PMID 38361581, 2024).
cardiac arrest (4 papers, 2019 to 2024). Cessation of breathing and/or cardiac function. "We recently investigated the gene expression of both cold-shock proteins RNA-binding motif 3 (RBM3) and CIRBP in patients treated with targeted-temperature management (33°C for 24 h) after cardiac arrest." (PMID 38361581, 2024). "In an in vivo model of deep hypothermic cardiac arrest, knockdown of CIRBP resulted in decreased cerebral injury and neuronal cell death." (PMID 34776788, 2021).
heart failure (4 papers, 2021 to 2025). Inability of the heart to pump blood at an adequate rate to meet tissue metabolic requirements. "Downregulated expression of cold-inducible RNA binding protein (CIRP), a stress-response protein, has been demonstrated in the hearts of patients with heart failure (HF)." (PMID 38539067, 2024).
ischemic stroke (3 papers, 2024 to 2025). A stroke disorder caused by obstruction of blood flow to the brain, due to thrombotic (local blood clot formation) or embolic (due to a blood clot or other material traveling from another site) event. "Low-temperature exposure promotes platelet activation by up-regulating CIRBP to activate the P-AKT signaling pathway, thereby increasing the risk of ischemic stroke." (PMID 40563401, 2025). "The present study aimed to investigate the role of neuronal cold-inducible RNA-binding protein (CIRP) in promoting NETs-induced brain endothelial barrier destruction and cerebral edema after ischemic stroke." (PMID 38377019, 2024).
lung carcinoma (3 papers, 2021 to 2024). "Together, this evidence demonstrates that DHA reduces irradiation-induced mitophagy and radioresistance in lung cancer A549 cells via CIRBP inhibition." (PMID 36013308, 2022). "In conclusion, we believe that DHA reduces radiation-induced mitophagy and radioresistance of lung cancer A549 cells via CIRBP inhibition." (PMID 36013308, 2022).
melanoma (3 papers, 2017 to 2020). A malignant, usually aggressive tumor composed of atypical, neoplastic melanocytes. "The results of our study showed that CIRBP could induce HIF-1α protein production via a CIRBP-mediated increase in mRNA stability in BCa, and the same results had been reported in Melanoma LOX-IMVI cells in a study by Chang et al51." (PMID 30315244, 2018).
memory impairment (3 papers, 2024 to 2025). "Research has demonstrated that CIRBP plays a role in alcohol-induced memory impairment." (PMID 40779572, 2025).
nasopharyngeal carcinoma (3 papers, 2020 to 2022). A carcinoma arising from the nasopharyngeal epithelium. "Loss of CIRBP expression is correlated with the malignant progression and poor prognosis in nasopharyngeal carcinoma." (PMID 35778922, 2022). "Previous studies have also linked loss of CIRBP expression with malignant progression of nasopharyngeal carcinoma." (PMID 32899298, 2020).
pulmonary fibrosis (3 papers, 2022 to 2025). Chronic progressive interstitial lung disorder characterized by the replacement of the lung tissue by connective tissue, leading to progressive dyspnea, respiratory failure, or right heart failure. "Cold-inducible RNA-binding protein (CIRBP) is a relatively recent focus in pulmonary fibrosis research." (PMID 40351459, 2025). "CIRBP plays a crucial role in cellular stress responses, and its expression levels in pulmonary fibrosis correlate with disease severity, making it a potential biomarker for monitoring disease progression and assessing treatment efficacy." (PMID 40351459, 2025).
Stroke (3 papers, 2024 to 2025). Sudden impairment of blood flow to a part of the brain due to occlusion or rupture of an artery to the brain. "One such peptide, Tat–cold-inducible RNA binding protein (Tat-CIRP), has shown neuroprotective properties in animal models of stroke." (PMID 40723833, 2025).
adenoma (2 papers, 2016 to 2025). A neoplasm arising from the epithelium. "Conversely, SMAD9 showed a significant upregulation in adenoma, while CIRBP was downregulated only in tumors." (PMID 39980011, 2025).
alcohol (2 papers, 2019 to 2020). "We have also demonstrated the involvement of a stress response protein, cold inducible RNA binding protein (CIRP), as a potential mechanistic mediator in acute alcohol intoxication." (PMID 32116535, 2020).
Arthritis (2 papers, 2013 to 2024). Inflammation of a joint. "The CIRBP-dependent regulation of IL-1β and NF-κB could be important in a variety of disease states including autoimmune disorders, arthritis and cancer." (PMID 23437386, 2013).
Breast Tumor (2 papers, 2015 to 2024). "Hypermethylation of the LZTS1 transcription start site did not exhibit an association with expression in TCGA breast tumours; however, FOXA1 (R2 ≤ 0.75 and 0.67 for regions A and B, respectively) and CIRBP (R2 ≤ 0.212) both exhibited loss of expression with increased methylation." (PMID 25960784, 2015).
colorectal cancer (2 papers, 2013 to 2020). A primary or metastatic malignant neoplasm that affects the colon or rectum. "CIRBP was originally identified as a UVC-induced transcript in CHO cells and this was later extended to human colorectal cancer cells." (PMID 23437386, 2013).
cryptorchidism (2 papers, 2016 to 2024). The failure of one or both testes of a male fetus to descend from the abdomen into the scrotum during the late part of pregnancy.
glioma (2 papers, 2021 to 2024). A benign or malignant brain and spinal cord tumor that arises from glial cells (astrocytes, oligodendrocytes, ependymal cells). "In this study, we focused on CIRBP and conducted preliminary research on its role in glioma ferroptosis." (PMID 39857625, 2024). "To assess the role of CIRBP in ferroptosis, we analyzed its effect on erastin-induced and ferrostatin 1-inhibited ferroptosis in glioma cells and expression of GPX4 and SLC7A11, which are markers of ferroptosis." (PMID 39857625, 2024). "After ferroptosis induction in gliomas, CIRBP expression increased, with notably higher expression in low-grade gliomas than in high-grade gliomas." (PMID 39857625, 2024). "Inversely, CIRBP knockout in glioma cells promoted glioma cell proliferation and reduced their sensitivity to erastin-induced ferroptosis." (PMID 39857625, 2024). "Our experimental results and survival curve analysis revealed that patients with glioma with high CIRBP expression had longer overall survival periods." (PMID 39857625, 2024). "However, the specific mechanisms by which CIRBP influences ferroptosis and glioma progression warrant further research to comprehensively elucidate its therapeutic potential." (PMID 39857625, 2024). "Patients with low CIRBP expression generally have a worse prognosis than those with high CIRBP expression, suggesting that CIRBP may play a role as a tumor suppressor gene in gliomas." (PMID 39857625, 2024). "Although CIRBP is associated with ferroptosis, its role in glioma has not yet been extensively studied." (PMID 39857625, 2024). "We investigated transcriptional changes after glioma cell ferroptosis, dissected the function and potential regulatory relationships among differentially expressed mRNAs and lncRNAs, and explored whether cold-inducible RNA-binding protein (CIRBP) promotes glioma cell ferroptosis." (PMID 39857625, 2024). "However, the specific role of CIRBP in glioma ferroptosis remains unclear." (PMID 39857625, 2024).
infiltrating ductal carcinoma (2 papers, 2020 to 2021). "The feature plots and spatial feature plots were utilized to illustrate the distribution and expression of CIRBP, FAM110B, ACAA1, ACAT1, and DHCR7, showing that these key genes were highly expressed in the invasive ductal carcinoma tissue (cluster 2, 5, 8)." (PMID 32984314, 2020). "To test whether CIRBP levels can function as a prognosis factor, we explored CIRBP transcript prevalence in ER+PR+ patients with primary infiltrating ductal carcinoma and negative lymph node status." (PMID 33172965, 2021).
inflammatory bowel disease (2 papers, 2023 to 2024). A spectrum of small and large bowel inflammatory diseases of unknown etiology. "ETS1 has also been linked to CD, as it is highly expressed in CD4+ T-cells from patients with inflammatory bowel disease and promotes Th1-driven mucosal inflammation through cold-inducible RNA binding protein (CIRBP)." (PMID 37048094, 2023).
myocardial ischemia (2 papers, 2017 to 2024). A disorder of cardiac function caused by insufficient blood flow to the muscle tissue of the heart. "In the context of CAD, abnormal expression of CIRBP may reflect the hypoxic and oxidative stress status faced by myocardial cells, which is closely related to myocardial ischemia caused by coronary artery stenosis." (PMID 39610972, 2024). "Cold inducible RNA-binding protein (CIRBP) is reported to be involved in multiple pathological processes, including myocardial ischemia." (PMID 28355355, 2017). "The present study provided a new understanding of the regulation of CIRBP in myocardial ischemia injury and identified potential avenues for therapeutic intervention of this disease." (PMID 28355355, 2017). "In this study, we investigated cell viability, apoptosis, and reactive oxygen species (ROS) of H9C2 cells in vitro, and confirmed the connection between CIRBP and myocardial ischemia injury." (PMID 28355355, 2017). "In the present study, the ROS level in cells with myocardial ischemia was significantly reduced by CIRBP overexpression while markedly enhanced by CIRBP knockdown." (PMID 28355355, 2017). "The involved pathway of CIRBP in myocardial ischemia injury was also investigated." (PMID 28355355, 2017). "Our study revealed that CIRBP could protect H9C2 cells against myocardial ischemia through inhibition of NF-κB pathway." (PMID 28355355, 2017). "Thus, the effects of CIRBP on myocardial ischemia could be connected with the NF-κB pathway activation." (PMID 28355355, 2017). "Thus, we confirmed that CIRBP could promote cell proliferation in myocardial ischemia cells." (PMID 28355355, 2017). "Thus, we concluded that CIRBP could inhibit cell apoptosis in myocardial ischemia cells." (PMID 28355355, 2017). "In our study, the expression level of Bcl-3 was markedly up-regulated by CIRBP overexpression, which might be another explanation for the effect of CIRBP on proliferation and apoptosis of H9C2 cells with myocardial ischemia." (PMID 28355355, 2017).
pancreatic adenocarcinoma (2 papers, 2016 to 2025). "Multivariate Cox regression analysis of the seven candidate prognostic MDRGs identified CITED4 and CIRBP as independent prognostic factors for both OS and disease-specific survival (DSS) in patients with pancreatic adenocarcinoma." (PMID 40303346, 2025).
systemic sclerosis (2 papers, 2023 to 2025). A chronic disorder, possibly autoimmune, marked by excessive production of collagen which results in hardening and thickening of body tissues. "Although CIRBP remains unexplored in MG pathogenesis, emerging evidence from autoimmune research has established significant associations between elevated CIRBP expression and clinical severity in rheumatoid arthritis and systemic sclerosis." (PMID 40622977, 2025).
viral infection (2 papers, 2021 to 2024). "Interestingly, endoplasmic stress induced by viral infection promoted the loss of m6A in CIRBP, and the expression of the short isoform of CIRBP positively regulated HCV replication." (PMID 33742132, 2021). "Research has demonstrated that ER stress responses activated by viral infection are involved in m6A changes in RIOK3 or CIRBP." (PMID 39072324, 2024). "During viral infection, m6A modification of RIOK3 promotes its translation, while reduced m6A modification of CIRBP promotes alternative splicing." (PMID 39072324, 2024).
alcohol addiction (1 paper, 2022). "Furthermore, Naltrexone (NTX), a commonly accepted treatment for drug and alcohol addiction as well as a potent antagonist of OGFR 13, 15, 24, successfully rescued the increase in apoptosis induced by CIRBP knockdown." (PMID 35541895, 2022).
amyloid (1 paper, 2020). "In conclusion, we demonstrate a neuroprotective effect of CIRBP against Aβ induced-cytotoxicity through antioxidative and antiapoptotic pathways in rat primary cortical neurons, which may provide a novel therapeutic strategy for amyloid-based AD prevention or therapy." (PMID 32184914, 2020).
autoimmune disorders (1 paper, 2025). "This cross-disease validation strengthens the hypothesis that CIRBP dysregulation represents a conserved pathogenic mechanism in autoimmune disorders, potentially serving as a novel therapeutic target for MG management." (PMID 40622977, 2025). "Our research extends these findings to MG, demonstrating that elevated CIRBP levels represent a ubiquitous phenomenon in autoimmune disorders, suggesting a shared mechanism of immune dysregulation." (PMID 40622977, 2025). "Although no direct studies have investigated the relationship between CIRBP and MG, we propose a potential link based on CIRBP’s established role in immune regulation and the recognition of circadian clock genes as contributing factors in autoimmune disorders." (PMID 40622977, 2025).
breast ductal carcinoma (1 paper, 2021). "Depletion of CIRBP from luminal A MCF-7 breast ductal carcinoma cells resulted in decreased proliferation and clonogenicity while, conversely, CIRBP overexpression in nontumoral breast MCF-10A cells increased these traits." (PMID 33172965, 2021).
cerebral infarction (1 paper, 2023). An ischemic condition of the brain, producing a persistent focal neurological deficit in the area of distribution of the cerebral arteries. "While animal studies have suggested a correlation between cold-inducible RNA-binding protein (CIRP) serum levels and the severity and prognosis of cerebral infarction, there has been a lack of research exploring this association in humans with cerebral infarction." (PMID 37521290, 2023).
cervical cancer (1 paper, 2023). A primary or metastatic malignant neoplasm involving the cervix. "Cervical cancer was found to have dysregulation in two ATTS regulatory factors: cold-inducible RNA binding protein (CIRP, also known as CIRBP or A18 hnRNP), which binds and stabilizes pro-survival gene transcripts, and RBBP6, which suppresses polyadenylation." (PMID 37176052, 2023).
congenital heart disease (1 paper, 2022). A heart disease that is present at birth. "Chronic hypoxia characterized in cyanotic congenital heart disease rendered CIRBP promoter hypermethylation in turn reducing CIRBP hypothermic elicitation and crippling its cytoprotective potency, indicative of the importance of CIRBP in cardioprotection." (PMID 35541895, 2022).
glioblastoma (1 paper, 2024). The most malignant astrocytic tumor (WHO grade IV). "Our findings highlight the relationship between CIRBP expression and ferroptosis in glioblastoma cells." (PMID 39857625, 2024). "This improved understanding of the role of CIRBP in ferroptosis paves the way for more precise and efficacious treatments for glioblastoma, potentially improving patient outcomes." (PMID 39857625, 2024). "We demonstrated that CIRBP modulates key aspects of cell death, thereby altering the sensitivity of glioblastoma cells to erastin-induced ferroptosis." (PMID 39857625, 2024).
gynecologic cancers (1 paper, 2024). "Shang and colleagues reported the hypermethylation and downregulation of CIRBP were associated with poor prognosis in gynecologic cancers." (PMID 38695555, 2024).
nasal polyps (1 paper, 2022). "A recent study suggested that cold-inducible RNA-binding protein (CIRP), a newly identified damage-associated molecular pattern (DAMP), could increase the number of macrophages producing MMPs and VEGF-A, thereby contributing to tissue edema and the formation of nasal polyps." (PMID 36466903, 2022).
neuroblastoma (1 paper, 2019). Neuroblastoma (NB) is the most common solid, extracranial childhood tumor. "Alleviation of oxidative stress has been attributed to CIRBP in mouse testes, hepatocytes, the neuroblastoma cell line neuro2a, and in rat cortical neurons, and to RBM3 in human SH-SY5Y neuroblastoma cells and C2C12 mouse myoblasts." (PMID 31443506, 2019).
sarcoma (1 paper, 2021). A usually aggressive malignant neoplasm of the soft tissue or bone. "As expected, NMR analysis of the methylation-free recombinant RG/RGG model proteins cold-inducible RNA-binding protein (CIRBP) and RNA-binding protein fused in sarcoma (FUS) revealed that ADMA and MMA are detectable in recombinant proteins after incubation with PRMT1 and the methyl donor SAM." (PMID 35475236, 2021).
ZIKV infection (1 paper, 2024). "More specifically, it has been shown that ZIKV infection decreases m6A content of CIRBP mRNA and increases the one of PUM2 and TNRC6A mRNAs." (PMID 39565347, 2024). "To study the impact of ZIKV infection on IGF2BP2 association with endogenous RNAs, we decided to focus our analysis on three known IGF2BP2 mRNA ligands namely CIRBP, TNRC6A, and PUM2." (PMID 39565347, 2024).